GLP2R (glucagon like peptide 2 receptor)
Description:
This is a receptor for glucagon-like peptide 2. The activity of this receptor is mediated by G proteins which activate adenylyl cyclase.
Tractability: Antibody: its Gene Ontology location is reachable by antibodies, with high confidence; UniProt places it where antibodies can reach, with medium confidence; UniProt predicts a signal peptide or a membrane-spanning region; the Human Protein Atlas places it where antibodies can reach. PROTAC: ubiquitination databases record sites on it; a small molecule that binds it is known. Other modalities: an approved drug acts on it.
Target class: Membrane receptor; Family B G protein-coupled receptor; Glucagon-like peptide receptor; Peptide receptor (family B GPCR); Glucagon-like receptor
Gene: Protein-coding gene on chromosome 17 (9,822,206 to 9,892,099, forward strand). Ensembl gene ENSG00000065325.
Subcellular location: Cell membrane
Subcellular location (Human Protein Atlas): Plasma membrane
Pathways (Reactome):
Signal Transduction: G alpha (s) signalling events; Glucagon-type ligand receptors
Gene Ontology:
Molecular function: G protein-coupled receptor activity; glucagon receptor activity; peptide hormone binding; transmembrane signaling receptor activity
Biological process: adenylate cyclase-modulating G protein-coupled receptor signaling pathway; positive regulation of cell population proliferation; cell surface receptor signaling pathway; cellular response to glucagon stimulus; G protein-coupled receptor signaling pathway
Cellular component: plasma membrane; membrane
Genetic constraint (gnomAD): Loss-of-function variants: 32 observed, 32.29 expected, observed/expected ratio (o/e) 0.99, 90% interval 0.75 to 1.33. The upper end of that interval is the gene's LOEUF score, 1.33, which puts it in group 5 of 6, group 1 being the genes least tolerant of losing a copy. Missense variants: 347 observed, 428.1 expected, observed/expected ratio (o/e) 0.81, 90% interval 0.74 to 0.89. Synonymous variants: 166 observed, 179.38 expected, observed/expected ratio (o/e) 0.93, 90% interval 0.81 to 1.05.
Homologues: Orthologues: chimpanzee GLP2R (99% identical), macaque GLP2R (97% identical), rat Glp2r (79% identical), dog GLP2R (78% identical), guinea pig GLP2R (78% identical), pig GLP2R (76% identical), mouse Glp2r (75% identical), rabbit GLP2R (72% identical), tropical clawed frog glp2r (48% identical). Paralogues in human: GLP1R (35% identical), GCGR (35% identical), GIPR (33% identical), SCTR (29% identical), VIPR1 (28% identical), PTH1R (28% identical), VIPR2 (27% identical), ADCYAP1R1 (27% identical), PTH2R (26% identical), GHRHR (25% identical), CALCRL (21% identical), CALCR (20% identical), and 30 more.
Diseases named in the same sentence as GLP2R in open-access papers:
GLP2R is named in the same sentence as 35 diseases in open-access papers, as found by Europe PMC text mining. Sharing a sentence is not in itself a finding about the gene and the disease. The quoted sentences say what the papers report.
Obesity (6 papers, 2009 to 2024). Accumulation of substantial excess body fat. "In this view, GLP-2R has been recently proposed as a target for the treatment of obesity." (PMID 39339669, 2024). "Therefore, blockade of the GLP‐2R signal could theoretically reduce general nutrient absorption pointing towards a potential role for GLP‐2R antagonists in the treatment of obesity." (PMID 35523760, 2022).
short bowel syndrome (4 papers, 2023 to 2026). "Glepaglutide is a long-acting GLP-2R agonist developed by Zealand Pharma and is currently in clinical development for the treatment of short bowel syndrome." (PMID 36944922, 2023). "Additionally, GLP-2r agonists are also being investigated for the treatment of other intestinal disorders such as intestinal fistulas and short bowel syndrome." (PMID 40070478, 2025). "Glepaglutide is a long-acting GLP-2R agonist in clinical development for short bowel syndrome." (PMID 36944922, 2023). "The GLP2R is the target of the medication teduglutide, a GLP2 analog used in pediatric and adult patients with intestinal failure secondary to short bowel syndrome, yet much remains unknown about the in vivo function of this receptor outside of mouse models." (PMID 39610412, 2024). "The glucagon‐like peptide‐2 receptor (GLP2R) is a G‐protein‐coupled receptor involved in intestinal growth and adaptation, which has gained increasing attention with the use of teduglutide, a recombinant glucagon‐like peptide‐2 (GLP2) analog, for children and adults with short bowel syndrome." (PMID 39610412, 2024).
Crohn disease (3 papers, 2012 to 2025). A gastrointestinal disorder characterized by chronic inflammation involving all layers of the intestinal wall, noncaseating granulomas affecting the intestinal wall and regional lymph nodes, and transmural fibrosis. "For example, GLP-2r agonists have been used in the treatment of inflammatory bowel diseases (such as Crohn’s disease and ulcerative colitis) because they can promote intestinal mucosal repair and regeneration, improving patients’ symptoms and quality of life." (PMID 40070478, 2025). "Glucagon-like peptides (GLP-1 and GLP-2) are two proglucagon-derived intestinal hormones that mediate distinct physiological functions through two related receptors (GLP-1R and GLP-2R) which are important drug targets for metabolic disorders and Crohn’s disease, respectively." (PMID 33239759, 2020).
diabetes (3 papers, 2019 to 2024). "GLP2R (rs17676067) is a receptor for glucagon-like peptide 2, which has been reported as associated with diabetes." (PMID 36313769, 2022).
colon neoplasms (2 papers, 2021 to 2023). "The GLP2 (secreted through colon tumor cells) binds to GLP2R expressed by carcinoma-related fibroblasts." (PMID 37076536, 2023). "GLP-2R transcripts are expressed in human colorectal tumors and GLP-2R protein is expressed in human colon neoplasms." (PMID 34660576, 2021).
gastric cancer (2 papers, 2022). A primary or metastatic malignant neoplasm involving the stomach. "The cellular functional experiments were used to investigate the potential role of GLP2R in gastric cancer." (PMID 35399509, 2022). "Furthermore, GLP2R knockdown significantly inhibited the proliferation, migration of gastric cancer cells in vitro." (PMID 35399509, 2022). "Finally, GLP2R may be expected to be a potential target for gastric cancer." (PMID 35399509, 2022). "Therefore, in order to investigate whether it can be used as a prognostic indicator, we performed in gastric cancer cell lines (BGC823, MKN45) and found that knockdown of GLP2R can significantly inhibit the proliferation and migration of gastric cancer cell lines." (PMID 35399509, 2022).
cervical cancer (1 paper, 2022). A primary or metastatic malignant neoplasm involving the cervix. "However, only a few studies using immunohistochemical methods have reported the expression of GLP2R in a limited number of tumor types, including ileal carcinoid, gastrointestinal stromal tumors and cervical cancer." (PMID 35027025, 2022).
Cognitive impairment (1 paper, 2020). Abnormal cognition is characterized by deficits in thinking, reasoning, or remembering. "In contrast, decreased GLP2R resulted in cognitive impairment in Sprague-Dawley rats subjected to chronic cerebral hypoperfusion." (PMID 32531902, 2020).
colitis (1 paper, 2022). Inflammation of the colon. "However, the level of GLP-2R was reduced in colitis in both mice and patients." (PMID 35893911, 2022).
colon adenocarcinoma (1 paper, 2021). "MYH11 positively modulated the immune-related gene GLP2R in colon adenocarcinoma." (PMID 34109184, 2021).
colon carcinoma (1 paper, 2020). "Indeed, our study shows that SSTR1+ and GLP-2R+ cells produce their own corresponding ligands in normal crypts as well as in colon carcinomas (SST and GLP-2, respectively)." (PMID 33112876, 2020).
colorectal cancer (1 paper, 2025). A primary or metastatic malignant neoplasm that affects the colon or rectum. "GLP2R has been identified as a significantly downregulated gene in colorectal cancer and is strongly associated with immune cell infiltration." (PMID 40893943, 2025).
depression (1 paper, 2022). "In the hippocampus, in addition to a decrease in the level of SNAP-25 in the model of depression and the coexistence of depression and hypothyroidism, there was also a decrease in the level of the receptor for glucagon-like peptide 2 (GLP-2R) in all three tested models." (PMID 35951260, 2022).
liver cancer (1 paper, 2024). An epithelial or non-epithelial malignant neoplasm that arises from the liver. "Among these, six genes were significantly differentially expressed between liver cancer tissue and adjacent normal tissue (CSAD, SLC16A11, LILRA2, IMMP2L, GLP2R, and DHDH)." (PMID 38927691, 2024).
lung carcinoma (1 paper, 2022). "The development of GLP-2 or GLP2R inhibitors may be beneficial to the clinical treatment of lung cancer." (PMID 35027025, 2022). "This study aims to reveal the role of glucagon-like peptide (GLP) 2 and GLP-2 receptor (GLP2R) signaling on the EGFR-TKIs and cisplatin resistance of lung cancer cells." (PMID 35027025, 2022).
mucositis (1 paper, 2021). Mucositis is inflammation and damage of the mucous membranes lining the mouth and other parts of the gastrointestinal (GI) tract. "The only difference we found between the GLP-2R(-/-) mice and their WT littermates in the acute phase of mucositis was significantly lesser increased myeloperoxidase activity in the WT mice." (PMID 33430185, 2021). "Similar losses in body weight were observed in GLP-2R(-/-) and wild type (WT) mice induced with mucositis during the first three days." (PMID 33430185, 2021). "Our current results show that GLP-2R signalling did not influence intestinal parameters during acute mucositis." (PMID 33430185, 2021).
osteosarcoma (1 paper, 2021). A usually aggressive malignant bone-forming mesenchymal neoplasm, predominantly affecting adolescents and young adults. "Previously, expression of the GLP-2r had been detected in human osteosarcoma-derived MG-63 and TE-85 cell lines." (PMID 34421828, 2021).
Smith-Magenis syndrome (1 paper, 2016). Smith-Magenis syndrome (SMS) is a complex genetic disorder characterized by variable intellectual deficit, sleep disturbance, craniofacial and skeletal anomalies, psychiatric disorders, and speech and motor delay. "Variants in the SMCR8 gene (Smith-Magenis Syndrome Chromosome Region, candidate 8; no OMIM #) and the GLP2R (Glucagon-Like Peptide 2 Receptor, OMIM #603659)) gene also showed increased LOD scores when the grandmother was coded as affected." (PMID 27120335, 2016).
tumor (6 papers, 2015 to 2024). "Gene expression analysis through TCGA-CRC data, GEPIA, and TIMER has shown the downregulation of GLP2R in the tumor samples as compared to the normal samples." (PMID 37076536, 2023). "The expression of STC2, ESM1, INHBA, CXCL1 and TDGF1 was significantly increased in tumor tissues than in normal tissues, whereas GLP2R expression was higher in normal tissues than in tumor tissues." (PMID 32788867, 2020). "The expression of RSPO3, ALPP, VEGFC, ANXA8, HES2, GLP2R, and KRT14 in normal tissues was significantly higher than that in tumor tissues." (PMID 38240936, 2024). "The overall survival analysis had finalized GLP2R and VSTM2A genes that were significantly downregulated in tumor samples and had a strong correlation with immunocyte infiltration." (PMID 37076536, 2023). "Meanwhile expression of gene DPT, SMOC2, GLP2R, FBLN5 and LMOD1 were down-regulated in tumor tissues." (PMID 25970782, 2015).
cancer (3 papers, 2022 to 2023). A tumor composed of atypical neoplastic, often pleomorphic cells that invade other tissues. "At the same time, we demonstrates that increased GLP2R expression is attached to an increase in cancer cell sensitivity to decitabine." (PMID 35399509, 2022). "There is little known about the relationship between GLP2R and cancer, but local activation of GLP2R diminishes islet inflammation by attenuating macrophage activation." (PMID 36523987, 2022).
gastrointestinal disorders (1 paper, 2024). "AEs at the SOC level revealed gastrointestinal disorders as the most prevalent, a foreseeable outcome given the localization of glucagon-like peptide-2 receptor (GLP-2R) in the gastrointestinal tract." (PMID 39329127, 2024).
neurodegenerative disease (1 paper, 2022). A disorder of the central nervous system characterized by gradual and progressive loss of neural tissue and neurologic function. "Several regulated genes, such as Arpc3, Glp2r, Sirt3 and Per1 have been reported to exert protective effects in neurodegenerative diseases or reverse memory deficits in various models, underlining the observed protective effects of spermidine." (PMID 35780157, 2022).
GLP2R also shares sentences with these, for which no sentence is quoted: autism (1 paper); colorectal tumors (1); gastrointestinal stromal tumor (1); hypothyroidism (1); inflammatory bowel disease (1); Insulin resistance (1); intestinal disorder (1); metabolic disorders (1); mood disorder (1); neurodevelopmental disorder (1); schizophrenia (1); type 2 diabetes (1); ulcerative colitis (1).